SMARCB1 (SWI/SNF related BAF chromatin remodeling complex subunit B1)
Diseases named in the same sentence as SMARCB1 in open-access papers (continued):
Sharing a sentence is not in itself a finding about the gene and the disease.
meningioma (continued). "CREBBP, PIK3CA (R108H), PIK3R1, BRCA1, and SMARCB1 are the most represented mutations; unfortunately, none of these mutations can predict the rate of recurrence in NF2-mutated meningiomas." (PMID 35892898, 2022). "Sporadic multiple meningiomas have been associated with somatic NF2 mutations and, to date, there has been no case related to somatic SMARCB1 mutations." (PMID 30416484, 2018). "Pathology confirmed the masses as meningiomas, WHO Grade I. Tumor genetic testing was positive for SMARCB1 mutation but blood genetic testing was negative for SMARCB1 mutation." (PMID 30416484, 2018). "The present case demonstrates that NF2/SMARCB1-mutant meningiomas are not exclusive to midline sagittal localization but may be also intra-ventricular." (PMID 35049691, 2022). "SMARCB1 mutations, involved in gene expression regulation and also located in close proximity to NF2 on chromosome 22, have also been identified in particularly atypical meningiomas in prior work, but were not identified in our matched tumor pairs." (PMID 31191822, 2019). "Importantly, when we screened our cohort of 110 primary, non-recurrent meningiomas (n=66 NF2 atypical, n=12 NF2 benign CNV-high, n=4 non-NF2 benign, CNV-high, n=12 NF2 benign CNV-low, n=12 non-NF2 benign CNV-low and n=4 NF2/SMARCB1), we did not identify any TERT promoter mutations." (PMID 28195122, 2017).
chordoma (63 papers, 2013 to 2026). Chordomas are rare malignant tumors arising from embryonic remnants of the notochord in axial skeleton. "Using DNA methylation analysis, we characterized the molecular subtypes among chordomas in children and the SMARCB1 (INI1)-deficient tumours, which was further complemented by fluorescence in situ hybridization and targeted exome sequencing." (PMID 42293322, 2026). "These mutations affect various subunits of the SWI/SNF chromatin remodeling complex, with ARID1A being the most frequently mutated gene, followed by SMARCA4, ARID1B, ARID2, PBRM1, and SMARCB1, mutations we have found to be common in adult chordoma." (PMID 39941902, 2025). "Complete loss of the SMARCB1/INI1 nuclear protein has also been reported as a peculiar feature of poorly differentiated chordoma." (PMID 39199581, 2024). "Recently, the partial loss of SMARCB1/INI1 protein expression has been detected in conventional chordomas localized in the skull base." (PMID 39199581, 2024). "Recently, the concept of poorly differentiated chordoma, a subtype of chordoma characterized by loss of SMARCB1/INI1 with a poorer prognosis than conventional chordomas, was established." (PMID 38173946, 2024). "Monoallelic deletion of the SMARCB1 gene associated with co-deletion of the control region was observed in 16 cases of conventional chordoma (range 26–94%); 5 of these also had nuclei with additional copies of both signals." (PMID 39199581, 2024). "The four poorly differentiated chordomas exhibited complete loss of SMARCB1/INI1 in all the evaluated neoplastic cells." (PMID 39199581, 2024). "The partial loss of SMARCB1/INI1 expression has recently been reported in skull base conventional chordomas, with possible therapeutic implications." (PMID 39199581, 2024). "This classified the chordoma as a rare subtype of a poorly differentiated chordoma, exhibiting a deficiency in SMARCB1 expression." (PMID 38786326, 2024). "In recent years, an increasing number of tumors, including poorly differentiated chordomas, have been found to exhibit complete loss of SMARCB1/INI1 protein expression." (PMID 39199581, 2024). "In the case of epithelioid/solid forms, a loss of SMARCB1 (INI1) expression to confirm the diagnosis of poorly differentiated chordoma is mandatory." (PMID 36737790, 2023). "Epithelioid malignant peripheral nerve sheath tumour (eMPNST) and poorly differentiated chordoma (PDC) represent other SMARCB1‐deficient tumours." (PMID 37316954, 2023). "It has been evidenced that poorly differentiated chordomas, SMARCB1-deficient are associated with a poor outcome with high rates of metastases (30% of reported cases) and death (43% of reported cases)." (PMID 36737790, 2023). "In poorly differentiated chordomas, tumor cells are positive for broad-spectrum CKs and brachyury; they show loss of SMARCB1/INI1, and the S100 protein is rarely expressed." (PMID 37350949, 2023). "The loss of SMARCB1/INI1 protein has been recently described in poorly differentiated chordoma, an aggressive and rare disease variant typically arising from the skull base." (PMID 37456229, 2023). "Only few series have evaluated SMARCB1/INI1 immunohistochemical expression in association with FISH analysis in conventional chordoma." (PMID 37456229, 2023). "Loss of chromosome 22 and/or heterozygous deletion of SMARCB1 seems to be a rare event in conventional chordomas, although data are referred to small series." (PMID 37456229, 2023). "Fluorescence in situ hybridization (FISH) analysis was performed in 15/21 (71.4%) cases of the chordomas with partial SMARCB1/INI1 loss of expression." (PMID 37456229, 2023). "In chordomas, the loss of tumor suppression through SMARCB1/INI1 inactivation was considered as a new chordoma sub-group, more frequently affecting the young population and characterized by a poorer prognosis." (PMID 35326637, 2022).
chordoma (continued). "Recent studies explore the role of SMARCB1/INI-1 in chordoma, and the loss of SMARCB1/INI1 protein in poorly differentiated chordoma (PDC) associates not with point mutations but with SMARCB1/INI1 gene deletions instead." (PMID 36520826, 2022). "In chordoma, our previous study and other studies showed that the low expression or loss of SMARCB1 correlate with dismal survival." (PMID 34668612, 2021). "SWI/SNF‐related matrix‐associated actin‐dependent regulator of chromatin subfamily B member 1 (SMARCB1) loss is associated with a poor prognosis in chordoma, while the mechanism remains largely unclear." (PMID 34668612, 2021). "In chordoma, loss of SMARCB1 characterizes a novel subtype of chordoma with a dismal prognosis, namely poorly differentiated chordoma." (PMID 34668612, 2021). "We explored the immune microenvironment of poorly differentiated SMARCB1-deficient chordomas using CIBERSORT21 to estimate the relative abundance of immune cell types from RNA sequencing (RNA-seq) data." (PMID 34931022, 2021). "A previous study demonstrated that the downregulation of SMARCB1 expression is associated with the upregulation of miR-193a-5p and miR-671-5p expressions in pediatric chordomas." (PMID 32420340, 2020). "SMARCB1 loss is the defining marker of poorly differentiated chordomas (PDCs), a highly aggressive subtype distinct from dedifferentiated chordomas that occur most frequently in children and at the skull base." (PMID 32733369, 2020). "Some trials are currently evaluating clinical efficacy of an EZH2 inhibitor named Tazemetostat in patients with poorly differentiated chordoma with SMARCB1 loss (NCI# NCT02601950 and NCT02601937)." (PMID 32676456, 2020). "Similarly, a subtype of chordomas (poorly differentiated subtype), a rare tumour of the spine and base of skull, is associated with loss/inactivation of SWI/SNF Related Matrix Associated Actin Dependent Regulator Of Chromatin, Subfamily B, Member 1 (SMARCB1)." (PMID 37828086, 2025). "Thus, clinical trials on inhibitors of the EZH2 enzyme are currently underway in tumors with complete loss of SMARCB1/INI1 expression, including poorly differentiated chordomas (ClinicalTrials.gov Identifiers: NCT02601950 and NCT05407441)." (PMID 39199581, 2024). "Poorly differentiated chordomas presented loss of SMARCB1/INI1 in all evaluated neoplastic cells." (PMID 37456229, 2023). "However, recent work that studied a cohort of CNS tumors with SMARCB1 deficiency showed that poorly differentiated chordomas, SMARCB1-deficient constitute a different cluster." (PMID 36737790, 2023). "This nosology clearly distinguishes four clinicopathological forms of chordomas: conventional, chondroid, dedifferentiated (which have historically represented the pejorative evolution of a classical chordoma following radiation therapy) and the poorly differentiated chordoma, SMARCB1-deficient." (PMID 36737790, 2023). "Based on literature data, total loss of SMARCB1/INI1 immunohistochemical expression associated with the presence of a homozygous deletion of the SMARCB1 gene is correlated with aggressive clinical behavior of chordomas." (PMID 37456229, 2023). "FISH analysis could be performed with a readable signal in 15/21 (71.4%) cases of conventional chordomas with a partial immunohistochemical loss of SMARCB1/INI1 expression." (PMID 37456229, 2023). "Pathogenic SMARCB1 variants were found in 2 patients with chordoma." (PMID 37966258, 2023). "Recent studies have described the immunohistochemical loss of SMARCB1/INI1 protein in poorly differentiated chordoma associated with SMARCB1 gene deletions at fluorescence in situ hybridization (FISH) examination, mainly deriving from large, homozygous deletions at 22q11 locus." (PMID 37456229, 2023).
chordoma (continued). "Notably, biallelic loss of SMARCB1 defines an aggressive, poorly differentiated histopathological subtype of chordoma (<5% of cases) that most commonly afflicts the pediatric patient population." (PMID 36387127, 2022). "Poorly differentiated chordoma showed loss expression of SMARCB1 (INI1)." (PMID 36601478, 2022). "Moreover, recent studies proposed chordoma with SMARCB1 loss as a potential novel subset of chordoma, poorly differentiated chordoma, which displays aggressive behaviour and a dismal prognosis." (PMID 34668612, 2021). "Moreover, we identified ATG5 as a direct downstream target of SMARCB1 and revealed the association between autophagy and SMARCB1 in chordoma." (PMID 34668612, 2021). "Loss of SMARCB1 expression in chordoma has also been identified in poorly differentiated chordomas." (PMID 34070849, 2021). "However, the biological function and underlying mechanism of SMARCB1 in chordoma remain to be elucidated." (PMID 34668612, 2021). "Pediatric chordoma is characterized by a higher prevalence of germline ARID1B indels (22% vs. 5% in adults) and more frequent loss of INI1 (SMARCB1), especially in poorly differentiated cases." (PMID 39941902, 2025). "This study aimed to compare SMARCB1/INI1 protein expression patterns in spinal conventional chordomas with genetic alterations detectable in the SMARCB1 gene by FISH, clinicopathological features, OS, and DFS." (PMID 39199581, 2024). "The most frequent molecular alteration detected in conventional chordoma was the monoallelic deletion of the 22q locus (including SMARCB1 gene)." (PMID 39199581, 2024). "Specifically, the chordomas with mosaic SMARCB1/INI1 expression showed mainly monoallelic 22q deletion, whereas the cases with clonal SMARCB1/INI1 expression were associated with different types of genetic patterns." (PMID 39199581, 2024). "In our series, we genetically investigated only conventional chordomas with impaired SMARCB1/INI1 pattern expression, and in 43.2% of the feasible cases, a monoallelic co-deletion of the SMARCB1 gene and the control region was observed." (PMID 39199581, 2024). "Loss of INI1 expression, encoded by SMARCB1, is characteristic of poorly differentiated chordomas more common in children and young adults." (PMID 37966258, 2023). "Beyond ES, EZH2 inhibitors have also shown efficacy in other SMARCB1-defective diseases in children, such as chordoma or ATRT, with 50% and 19% response rates, respectively." (PMID 35327458, 2022). "INI1, also known as SMARCB1, encodes an important core subunit of the SWI/SNF complex, the deficiency of which is associated with poorly differentiated chordoma." (PMID 36612259, 2022). "Based on the apparent EZH2 dependence bestowed by SWI/SNF alterations, a Phase II study is underway to explore repurposing of tazemetostat for SMARCB1-null chordoma (NCT02601950)." (PMID 36387127, 2022). "Based on the pre-efforts and exploration of PD-1-related immunotherapy and SMARCB1/INI1 in chordoma by a wide range of scholars, further studies should improve scale and breakthrough." (PMID 36520826, 2022). "Promising efficacy has been suggested with EZH2 inhibitors, especially in SMARCB1/INI1 tumors, including chordomas." (PMID 35326637, 2022). "We first established stably transfected SMARCB1 knockdown and overexpressing chordoma cells, and the efficiencies were checked by qRT‐PCR and Western blot." (PMID 34668612, 2021). "We also found augmentation of ATG5 expression in SMARCB1 knockdown cells and impaired ATG5 expression in SMARCB1‐overexpressing chordoma cells." (PMID 34668612, 2021). "Chordoma cells with SMARCB1 overexpression showed a delay in tumour growth compared with the vector group." (PMID 34668612, 2021).
chordoma (continued). "SMARCB1 inhibited the malignant phenotype of chordoma cells in vitro and in vivo, supporting a tumour suppressor role of SMARCB1 in chordoma." (PMID 34668612, 2021). "Chromosome 22q harbors an important SWI/SNF gene, SMARCB1/IN1, and the complete loss of SMARCB1 expression on immunohistochemistry due to homozygous SMARCB1 deletion has been used as a marker for a rare chordoma subtype, poorly differentiated chordoma." (PMID 33536423, 2021). "In summary, our findings confirmed the tumour suppressor role of SMARCB1 in chordoma in vitro and in vivo." (PMID 34668612, 2021). "The results indicated that SMARCB1 knockdown significantly promoted the migration and invasion of chordoma cells, whereas SMARCB1 overexpression attenuated the migration and invasion of UM‐Chor1 and MUG‐Chor1 chordoma cells." (PMID 34668612, 2021). "Taken together, these findings suggested that SMARCB1 knockdown induced autophagic flux in chordoma cells." (PMID 34668612, 2021). "Chromatin immunoprecipitation (ChIP) sequencing was used to investigate the mechanisms of SMARCB1 in chordoma." (PMID 34668612, 2021). "Together, these findings revealed that changes in SMARCB1 expression affected the malignant phenotype of chordoma cells." (PMID 34668612, 2021). "Together, these results indicated that ATG5‐mediated autophagy was essential for the malignant phenotype of SMARCB1 knockdown chordoma cells." (PMID 34668612, 2021). "Interestingly, poorly differentiated chordomas are molecularly distinct, marked by SMARCB1 deletion and subsequent loss of INI1 expression​​." (PMID 39193055, 2024). "In the four cases of poorly differentiated chordoma, FISH analyses revealed biallelic SMARCB1 deletions in two cases, a monoallelic deletion in one case, and a pattern with a monoallelic SMARCB1 deletion associated with an additional control region signal in one case." (PMID 39199581, 2024). "Additionally, mutations within the chromatin remodeling genes PBRM1, SETD2, and SMARCB1, which have previously been recognized as frequently altered in chordoma, were each identified in two patients." (PMID 39135136, 2024). "Therefore, to best of our knowledge, this is the largest study aimed at investigation the incidence of SMARCB1/INI1 loss in of conventional skull base chordomas, accounting for >95% of chordomas." (PMID 37456229, 2023). "In our series, 21 cases of conventional chordoma displayed partial loss of SMARCB1/INI1 expression at immunohistochemistry; 6 (28.6%) showed no readable signal at FISH analysis, due to the poor tissue quality." (PMID 37456229, 2023). "FISH identified homozygous SMARCB1 deletions in all 3 cases of poorly differentiated chordoma." (PMID 37456229, 2023). "Consistent with previous studies, homozygous SMARCB1 loss was observed in the 3 cases of poorly differentiated, but not in conventional chordoma." (PMID 37456229, 2023). "It’s possible of detecting this genetic alteration also in others midline tumors such as poorly differentiated chordomas, and this genetic alteration changes the prognosis and make it unexpectedly unfavorable compared to classical chordomas with SMARCB1 retained." (PMID 35433419, 2022). "The data show recent PD-1-related immunotherapy and SMARCB1/INI1 in chordoma were a shortage in research and there may be more research ideas in the future by scholars." (PMID 36520826, 2022). "Notably, SMARCB1 was shown to repress EZH2 and, accordingly, high levels of EZH2 have been reported in SMARCB1-deficient tumors, including ES, AT/RT, MRT and chordomas." (PMID 36078034, 2022). "Keywords associated with recent chemotherapy, PD-1-related immunotherapy, and SMARCB1/integrase interactor 1 (INI1) in chordoma were a shortage of research and there may be more research ideas in the future by scholars." (PMID 36520826, 2022). "Therefore, poorly differentiated chordoma with a characteristic SMARCB1 deficit is a potential candidate for ICI treatment." (PMID 36465398, 2022).